PREX2 (phosphatidylinositol-3,4,5-trisphosphate dependent Rac exchange factor 2)
Description:
Functions as a RAC1 guanine nucleotide exchange factor (GEF), activating Rac proteins by exchanging bound GDP for free GTP. Its activity is synergistically activated by phosphatidylinositol 3,4,5-trisphosphate and the beta gamma subunits of heterotrimeric G protein. Mediates the activation of RAC1 in a PI3K-dependent manner. May be an important mediator of Rac signaling, acting directly downstream of both G protein-coupled receptors and phosphoinositide 3-kinase.
Synonyms: P-Rex2; DEPDC2; DEP.2; FLJ12987; PPP1R129
Tractability: Antibody: its Gene Ontology location is reachable by antibodies, with medium confidence. PROTAC: ubiquitination databases record sites on it.
Gene: Protein-coding gene on chromosome 8 (67,951,955 to 68,237,032, forward strand). Ensembl gene ENSG00000046889.
Subcellular location (Human Protein Atlas): Endoplasmic reticulum
Pathways (Reactome):
Signal Transduction: CDC42 GTPase cycle; RAC1 GTPase cycle; RHOA GTPase cycle; Regulation of PTEN stability and activity
Gene Ontology:
Molecular function: GTPase activator activity; guanyl-nucleotide exchange factor activity; protein binding; protein serine/threonine kinase inhibitor activity
Biological process: G protein-coupled receptor signaling pathway; negative regulation of TOR signaling; regulation of small GTPase mediated signal transduction; intracellular signal transduction; signal transduction
Cellular component: cytosol; plasma membrane
Genetic constraint (gnomAD): Loss-of-function variants: 55 observed, 105.7 expected, observed/expected ratio (o/e) 0.52, 90% interval 0.42 to 0.65. The upper end of that interval is the gene's LOEUF score, 0.65, which puts it in group 2 of 6, group 1 being the genes least tolerant of losing a copy. Missense variants: 1,224 observed, 1,360.9 expected, observed/expected ratio (o/e) 0.9, 90% interval 0.86 to 0.94. Synonymous variants: 475 observed, 477.34 expected, observed/expected ratio (o/e) 1, 90% interval 0.92 to 1.07.
Cancer hallmarks: invasion and metastasis (promotes)
Homologues: Orthologues: chimpanzee PREX2 (98% identical), rabbit PREX2 (98% identical), pig PREX2 (98% identical), macaque PREX2 (97% identical), dog PREX2 (97% identical), guinea pig PREX2 (94% identical), rat Prex2 (94% identical), mouse Prex2 (93% identical), tropical clawed frog prex2 (85% identical), zebrafish prex2 (79% identical). Paralogues in human: PREX1 (58% identical), GPR155 (10% identical), DEPTOR (8% identical).
Diseases named in the same sentence as PREX2 in open-access papers:
PREX2 is named in the same sentence as 44 diseases in open-access papers, as found by Europe PMC text mining. Sharing a sentence is not in itself a finding about the gene and the disease. The quoted sentences say what the papers report.
melanoma (36 papers, 2012 to 2025). A malignant, usually aggressive tumor composed of atypical, neoplastic melanocytes. "Unusually for Rac-GEFs, the PREX2 gene is frequently mutated in human cancers, particularly melanoma and pancreatic cancer, and mutations are associated with melanoma tumorigenesis and tumour cell invasiveness." (PMID 40764335, 2025). "The corollary of these findings is that PTEN loss would upregulate the GEF activity of PREX2 and, consequently, stimulate RAC1 function, potentially rendering targeting of PREX2 in the context of PTEN-deficient melanoma a rational approach." (PMID 39636745, 2025). "Although PREX2 was dispensable for the initiation and progression of melanoma, its loss conferred sensitivity to clinically relevant therapeutics targeting the MAPK pathway." (PMID 39636745, 2025). "Although PREX2 mutations are detected in ∼26% of human melanoma samples, these broadly lack functional annotation." (PMID 39636745, 2025). "Oncogenic activity and the relatively high frequency of its mutated form in melanoma make PREX2 a potential therapeutic target and a candidate for melanoma-diagnostic panel." (PMID 39340537, 2024). "Recognized as an oncogene, PREX2 displays abnormal expression in various tumors, with mutations or abnormal expression observed in melanoma, breast, ovarian, prostatic, hepatocellular carcinoma, and pancreatic cancer." (PMID 38609982, 2024). "PREX2 mutations were frequently occurred in melanoma and were considered as new candidate drivers of pancreatic carcinogenesis." (PMID 37301854, 2023). "And we found there were both missense mutations and 3′-UTR piSNVs of PREX2 from the same sample in 5 samples of Skin-Melanoma and 1 sample of Panc-AdenoCA." (PMID 35654793, 2022). "The somatic mutation of PREX2 has been reported in several cancers including hepatocellular cancer, breast cancer, Melanoma and lung cancer." (PMID 36531058, 2022). "The overexpression of PREX2 in vivo initiated the expression of variant proteins, which were involved in oncogenic activity in melanoma cells." (PMID 34680938, 2021). "PREX2 non-synonymous variants have been found in 44.0% of a 25 patients cohort and in 14.0% of a 107 melanoma samples validation cohort." (PMID 32850962, 2020). "The potential importance of RAC1 function in melanoma is further underlined by the discovery of frequent alterations in PREX2, and to a lesser extent PREX1, which are guanine nucleotide exchange factors for RAC1." (PMID 31257073, 2019). "The analysis also found that a significant fraction of tumors contained rearrangements and mutations of a gene called PREX2, and experiments confirmed that cancer-associated mutations of PREX2 promoted the growth of human melanoma cells in mice." (PMID 28100393, 2017). "In 2015, as part of the Reproducibility Project: Cancer Biology, we published a Registered Report that described how we intended to replicate selected experiments from the paper "Melanoma genome sequencing reveals frequent PREX2 mutations"." (PMID 28100394, 2017). "It is established that PREX2 can be mutated in melanoma and pancreatic ductal adenocarcinoma, and that cancer-associated PREX2 mutations can promote both tumorigenesis in vivo and tumor cell invasiveness." (PMID 28100393, 2017). "The Reproducibility Project did not attempt to replicate this finding, but subsequent studies have reported the frequency of PREX2 mutations in human melanoma, including meta-analysis of 241 melanomas." (PMID 28100393, 2017). "This Registered Report describes theproposed replication plan of key experiments from ‘Melanoma genome sequencingreveals frequent PREX2 mutations’ by Berger and colleagues,published in Nature in 2012 (Bergeret al., 2012)." (PMID 25490935, 2014). "Prex2 is a negative regulator of PTEN (phosphatase and tensin homologue) and is mutated in melanoma, although the role of Prex2 tyrosine phosphorylation is yet to be determined." (PMID 25200860, 2014).
melanoma (continued). "Recently, PREX2, a phosphatidylinositol-3,4,5-trisphosphate-dependent Rac exchange factor 2, was found to be mutated in 14% of 107 melanoma cases." (PMID 25393105, 2014). "Recently, mutations in another member of the P-REX family, PREX2, have been reported; yet their role in melanoma disease remains to be clarified." (PMID 24416617, 2013). "Although some studies have indicated that truncating mutations may drive constitutive RAC-GEF activity, the impact of PREX2 mutation in melanoma remains contentious." (PMID 39636745, 2025). "Next, to both validate response data and develop a more tractable in vitro system to understand the role of PREX2 under treatment, we used CRISPR/Cas9-mediated gene editing to disrupt the expression of PREX2 or its close relative PREX1 in the PTEN-deficient WM266.4 melanoma line." (PMID 39636745, 2025). "In addition, frequently activated mutations in the PREX2 gene have been observed in melanomas, in the research, which further increase the possibility of PTEN loss occurring in melanomas." (PMID 37174106, 2023). "Mutations in the RhoGEF PREX2 were identified in melanoma patients, and expression of mutated PREX2 proteins in melanoma cells accelerates tumor growth following their grafting in mice Moreover, deletion of Prex1 expression prevents melanocyte migration during mice development." (PMID 34503171, 2021). "Whole genome sequencing analysis of 25 metastatic melanoma samples matched with germline DNA identified phosphatidylinositol-3,4,5-trisphosphate dependent Rac exchange factor 2 (PREX2) as a significantly mutated gene with mutation frequency of 14% in an extended study of 107 human melanomas." (PMID 34680938, 2021). "For example, PREX2 GEF activity was activated by mutations found in NRAS-mutant melanoma." (PMID 31906480, 2020). "Berger has reported that PREX2 somatic mutations render melanoma cells susceptible to oncogenic activities, which may perturb or inactivate one or more of its cellular functions." (PMID 30796242, 2019). "In a recent melanoma study, 27% of the cohort was identified to have PREX2 mutations." (PMID 30796242, 2019). "Second, mutation of PREX2 can accelerate human melanoma growth." (PMID 28100393, 2017). "Biological variability has confounded efforts to confirm the role of PREX2 mutations in melanoma." (PMID 28100393, 2017). "First, PREX2 was identified as a frequently mutated gene in human melanoma." (PMID 28100393, 2017). "Consequently, no conclusions could be drawn concerning the possible contribution of PREX2 mutations to melanoma growth." (PMID 28100393, 2017). "Here, we used genetically engineered mouse models and patient-derived BRAFV600E-driven melanoma cell lines to dissect the role of PREX2 in melanomagenesis and response to therapy." (PMID 39636745, 2025). "Together, these data suggest that the canonical GEF activity of PREX2 counteracts MAPK inhibition in BRAF PTEN melanoma." (PMID 39636745, 2025). "Our data suggest that p110β inhibition selectively sensitizes cells to MEK inhibition in the subset of PTEN-deficient melanomas harboring hyperactivation of RAC1 signaling, or broader dysregulation of the PREX2/RAC1/PI3Kβ axis." (PMID 39636745, 2025). "PREX2, previously recognized as an oncogene in diverse cancers, such as melanoma, hepatocellular carcinoma, lung carcinoma, and pancreatic ductal adenocarcinoma, is a GEF regulating Rac activity under activated PI3K and G-coupled receptor signaling." (PMID 38609982, 2024). "Accordingly, PREX2 is widely considered an oncogene due to its promotion of tumor proliferation, migration, and invasion in numerous neoplasms (i.e., glioma, melanoma, and breast, ovarian, prostatic, and pancreatic cancers) when mutated or overexpressed." (PMID 37048724, 2023). "Frequent PREX2 and PRG4 mutations was observed in melanoma and mutant PREX2 accelerated tumor formation." (PMID 35449126, 2022).
melanoma (continued). "The PREX2 gene plays oncogenic roles in human cancers, such as melanoma, since it is involved in PIK3CA-PTEN-AKT signaling pathway." (PMID 32850962, 2020). "In 2017, 100 primary melanoma samples were analyzed by targeted NGS for 35 melanoma-related genes, and PREX2 mutations were reported in 14 samples." (PMID 32850962, 2020). "The overexpression of Phosphatidylinositol-3,4,5-Trisphosphate Dependent Rac Exchange Factor 2 (PREX2) is observed in various tumors, including HCC; and the frequent PREX2 mutations in melanoma are associated with invasiveness." (PMID 30796242, 2019). "More recently, deep-sequencing approaches of melanoma samples of different melanoma types highlighted new melanoma driver genes such as PREX2, PPP6C, and RAC1." (PMID 24416617, 2013). "In summary, our studies indicate that cotargeting of the MAPK and PREX2/RAC1/p110β signaling axes may be an efficacious therapeutic strategy in BRAFV600E-driven melanoma." (PMID 39636745, 2025). "Targeting RAC1 activity via genetic disruption of PREX2 can enhance sensitivity to MAPK inhibition in BRAF-V600E–driven melanoma in vivo, although pharmacologic targeting of the RAC1 effector p110β also seems capable of enhancing responses to MAPK inhibition in vitro." (PMID 39636745, 2025). "Here, we demonstrate that genetic or therapeutic targeting of the PREX2/RAC1/p110β pathway can substantially enhance responses to MAPK targeting in BRAF-mutant melanoma both in vitro and in vivo, presumably through suppression of AKT/mTOR driven cell-cycle progression." (PMID 39636745, 2025). "Intriguingly, melanoma-associated RAC1-activating mutations seem to be mutually exclusive with PTEN loss, suggesting a scenario whereby loss of PTEN drives wild-type RAC1 activation via PREX2 activation." (PMID 39636745, 2025). "Targeting the RAC1-GTPase pathway, including the upstream activator PREX2 and the downstream effector PI3Kβ, could be a potential strategy for overcoming therapeutic resistance, limiting melanoma recurrence, and suppressing metastatic progression." (PMID 39636745, 2025). "In line with PREX2 deficiency, this mutation had no impact upon disease trajectory, with naevus onset, melanoma initiation, and overall survival of BRAF PTEN PREX2-GD animals equivalent to the BRAF PTEN control cohort." (PMID 39636745, 2025). "Overall, 30% of melanomas show alterations in either PREX1 or PREX2, although the functional significance of most of these individual changes has not been tested and may not all be mediated through RAC1 signaling." (PMID 31257073, 2019). "The authors identified the phosphatidylinositol-3,4,5-trisphosphate-dependent Rac exchange factor 2 gene (PREX2) as a significantly mutated gene (SMG) in this population and went on to confirm this finding in an independent cohort of 107 human melanoma samples." (PMID 28100394, 2017). "Furthermore, PREX2 and GRIN2A mutations were significantly more prevalent in melanomas with mitosis [p = 0.042; OR = 4.0 (1.0–15.4) and p = 0.023; OR = 6.2 (1.3–29.5), respectively]." (PMID 28356599, 2017). "Besides melanoma, PREX2 is also a potential driver of pancreatic and hepatocellular cancer." (PMID 39340537, 2024). "Interestingly, there was one Skin-Melanoma sample having four different missense mutations and 2 different 3′-UTR piSNVs of PREX2, who had higher levels of malignancy (IV, AJCC 7th Edition 2010), while other samples normally had simply one missense mutation or 3′-UTR piSNV." (PMID 35654793, 2022). "Significance: Cotargeting the MAPK and the PREX2/RAC1/PI3Kβ pathways has remarkable efficacy and outperforms monotherapy MAPK inhibition in BRAF-mutant melanoma, supporting the potential of this combination therapy for treating metastatic melanoma." (PMID 39636745, 2025).
melanoma (continued). "Cotargeting the MAPK and the PREX2/RAC1/PI3Kβ pathways has remarkable efficacy and outperforms monotherapy MAPK inhibition in BRAF-mutant melanoma, supporting the potential of this combination therapy for treating metastatic melanoma." (PMID 39636745, 2025). "To examine the role of PREX2 in melanoma, we interbred BRAF mice with germline deletion of Prex2 (Tyr-CreERT2BrafV600E/+Prex2−/− – henceforth BRAF PREX2)." (PMID 39636745, 2025). "Building on these observations, we use genetically engineered mouse models (GEMM) and xenografts to characterize the role of PREX2 and p110β in BRAFV600E-driven melanoma in vivo." (PMID 39636745, 2025). "Considering this, we tested the functional role of PREX2 in melanoma in vivo, combining GEMMs of BRAFV600E-mutant melanoma with constitutive Prex2 deletion." (PMID 39636745, 2025). "A truncating mutant of PREX2 in melanoma has increased Rac1 GEF activity, and activates PI3K/AKT signaling, while abolishing binding to the PTEN tumor suppressor in melanoma." (PMID 30261690, 2018). "Having demonstrated that the significant translational potential of cotargeting of MAPK and PREX2/RAC1/p110β, we next tested whether the same was true in immunocompetent, autochthonous melanoma GEMMs." (PMID 39636745, 2025). "PREX2 truncation E824∗ was found to cooperate with NRAS mutations but not with BRAF V600E mutation, to accelerate melanoma development." (PMID 32850962, 2020). "Although these evidences point to PREX2 as a key player in melanoma, suggesting that PREX2 may be a potential therapeutic target, to date no clinical trials are available." (PMID 32850962, 2020). "Our hypothesis was that if the enhanced response to MAPK observed following genetic targeting of PREX2 or pharmacologic targeting of p110β/δ acted via the same mechanism, no additional benefit for should be elicited by targeting melanomas lacking functional PREX2 with AZD8186." (PMID 39636745, 2025). "Although PREX2 was not reported as a SMG or a driver gene in previous GC-based studies, it was reported as a SMG in a study on melanoma, as well as being a candidate driver gene of pancreatic carcinogenesis." (PMID 34095982, 2021).
breast carcinoma (7 papers, 2017 to 2022). "The PTEN tail contains a PDZ domain, which interacts with the IP4P domain (ranging from 755 to 1606) of PREX2 and is sufficient to antagonize the PREX2-driven invasion when tested in breast cancer cells, BT549 and SUM149, and in human embryonic kidney, 293 cells." (PMID 30796242, 2019). "Interestingly, the module includes PREX2, which has been recently identified as a negative regulator of PTEN in breast cancer." (PMID 29023534, 2017).
hepatocellular carcinoma (6 papers, 2019 to 2024). A malignant tumor that arises from hepatocytes. "In the study of hepatocellular cancer, most mutant forms of PREX2, had an extended half-life compared with wild-type PREX2, and mutated PREX2 also promoted migration and activated the AKT pathway." (PMID 36531058, 2022). "PREX2 is a frequently mutated guanine nucleotide exchanger (GEF) in cancer, which interacts with the tumor suppressor PTEN to promote cell proliferation in colorectal, kidney, lung, and hepatocellular cancers." (PMID 38803565, 2024). "The somatic mutation S1113R of the phosphatidylinositol-3,4,5-trisphosphate dependent Rac exchange factor 2 (PREX2) gene has been shown to promote migration and proliferation and activate the AKT pathway in hepatocellular carcinoma (HCC)." (PMID 33807071, 2021).